ABCA1 (ATP binding cassette subfamily A member 1)
Diseases named in the same sentence as ABCA1 in open-access papers (continued):
Sharing a sentence is not in itself a finding about the gene and the disease.
Tangier disease (continued). "A deficiency of ABCA1 causes Tangier disease characterized by a marked reduction in HDL-C, orange tonsils, hepatosplenomegaly, and enhanced atherosclerosis." (PMID 37233667, 2023). "Tangier disease is a rare monogenic autosomal recessive disorder that occurs due to mutations in both alleles of the ABCA1 gene, both exonic and intronic in ABCA1 causing aberrant splicing of mRNA." (PMID 36651718, 2023). "Here, we show that total plasma sphingolipids were greatly reduced in patients with Tangier disease and apoB-lipoprotein free plasma of individuals with compound heterozygous ABCA1 mutations." (PMID 37601634, 2023). "ATP binding cassette transporter A1 (ABCA1) limits the formation of high density lipoproteins (HDL) as genetic loss of ABCA1 function causes virtual HDL deficiency in patients with Tangier disease." (PMID 37601634, 2023). "In this article, we sought to describe the pathogenicity of a homozygous variant in ABCA1 in a patient with suspected Tangier disease for an accurate characterization of the disease-causing variant." (PMID 37048678, 2023). "When this individual was subsequently correctly diagnosed they were found to have Tangier disease (familial alpha-lipoprotein deficiency), an ultra-rare inherited metabolic disorder that arises from mutations in ABCA1." (PMID 37844193, 2023). "We report the case of a patient referred to our clinic presenting features typical of Tangier disease with a likely pathogenic ABCA1 variant, c.4799A>G, identified for the first time as homozygous." (PMID 37048678, 2023). "Tangier disease (TD) is a rare autosomal recessive disorder caused by a variant in the ABCA1 gene, characterized by significantly reduced levels of plasma high-density lipoprotein cholesterol (HDL-C) and apolipoprotein A-1 (ApoA-I)." (PMID 37048678, 2023). "Two of the studied ABCA7 mutants, p.A845V and p.R1932C, are in conserved amino acid residues and mutations at these residues in ABCA1 or ABCA4 are known to cause Tangier disease or Stargardt disease respectively." (PMID 35361255, 2022). "ABCA1 is ubiquitously expressed in the body, and HDL generation is the only pathway for reverse cholesterol transport; thus, ABCA1 deficiency causes severe hypercholesterolemia or Tangier disease." (PMID 36395885, 2022). "We have identified one IC with a compound heterozygosity in LCAT causing Fish Eye Disease and one IC with a variant in ABCA1 in homozygosity causing Tangier disease." (PMID 37138899, 2022). "With homozygous cases of ABCA1 deficiency (Tangier disease), almost all the apoA1in plasma is found in the form of small prebeta HDL particles." (PMID 35460704, 2022). "ABCA1 is firstly detected as a mutated molecule in patients with Tangier disease, and the reduction of ABCA1 results in a severe deficiency of high-density lipoprotein (HDL) and cholesterol accumulation in the liver." (PMID 35057469, 2022). "Tangier disease is inherited as an autosomal recessive trait and is caused by pathogenic variants in the ABCA1, which mediates the secretion of cholesterol excess from cells into the HDL metabolic pathway." (PMID 37138899, 2022). "The Tangier disease caused by ABCA1 mutation cannot express ABCA1 protein, and LXRα and PPARγ cannot regulate the reverse transport of cholesterol, which directly proves the regulation of ABCA1 by PPARγ-LXRα pathway." (PMID 36557773, 2022). "Mutations in the ABCA1 gene are known to cause a rare genetic Tangier disease, which is characterized by a significant decrease in HDL levels and an increased incidence of cardiovascular disease." (PMID 36011386, 2022). "Tangier disease is caused by a mutation in the ABCA1 gene encoding the ATP-binding cassette transporter A1 (ABCA1), leading to impaired cholesterol efflux capacity." (PMID 34831381, 2021). "Tangier disease (TD) is a rare autosomal recessive disease caused by homozygous or compound heterozygous loss of function variants in both alleles of the ABCA1 gene (OMIM #205400)." (PMID 33562440, 2021).
Tangier disease (continued). "In mouse models with knocked out ABCA1 gene and among individuals with complete loss of ABCA1 function (Tangier disease), accumulation of large amounts of cholesterol in macrophages have been observed." (PMID 34547056, 2021). "ABCA1 plays an important role in cellular cholesterol removal, and ABCA1 gene mutations cause Tangier disease (OMIM #205400)—an autosomal recessive disease characterized by reduced levels of HDL-c and intracellular accumulation of cholesteryl esters." (PMID 34829957, 2021). "ABCA1 is firstly identified as a mutated molecule in Tangier Disease, with deficiency of high-density lipoprotein (HDL), accumulation of cholesterol in many cases, and glucose intolerance developing into diabetes." (PMID 34578896, 2021). "Patients with Tangier disease have mutations in the ABCA1 gene and present with mild proteinuria and foamy podocytes in kidney biopsy." (PMID 32733268, 2020). "Studies investigating the roles of ABCA1 in RCT have since observed similarities in the phenotype of ABCA1 deficient mice compared to the phenotype of human Tangier disease." (PMID 32977800, 2020). "Fibroblasts from patients with Tangier disease, who have an inherited ABCA1 mutation, show an increased content of the mitochondrial-specific phospholipid CL, while patients have reduced HDL levels in the blood." (PMID 32733268, 2020). "Mutations in ABCA1 can cause Tangier disease, a rare genetic disorder characterized by a substantial reduction in HDL levels." (PMID 32977800, 2020). "Mutations in the ABCA1 gene cause Tangier disease, which is characterized by extremely low plasma HDL-C levels and premature atherosclerosis." (PMID 33293505, 2020). "Twenty-two of the 48 human ABC transporters have been implicated in causing monogenetic diseases, such as Tangier disease (gene: ABCA1) and Dubin-Johnson syndrome (gene: ABCC2)." (PMID 30611276, 2019). "Mutations that inactivate ABCA1 lead to Tangier disease, a disorder characterized by increase extrahepatic tissue cholesterol accumulation, near-absence of plasma HDL, decrease plasma LDL concentrations, and increase plasma TG levels." (PMID 31635197, 2019). "It is well-known that patients with Tangier’s disease (with genetic mutations or deficiency in ABCA1) have very low serum HDL." (PMID 30679232, 2019). "Tangier disease due to ABCA1 deficiency is associated with very low HDL plasma levels and an upregulation of ABCG1 gene expression." (PMID 30611276, 2019). "ABCA1 mutation in humans results in Tangier Disease, which is characterized by low levels of ApoE and HDL in both the brain and plasma." (PMID 30373276, 2018). "Clinically, insulin secretion in patients with Tangier disease and the ABCA1 mutation is still under investigation." (PMID 30425683, 2018). "A known, but very rare autosomal recessive disorder caused by the lack of functional ABCA1 protein is called Tangier’s disease." (PMID 28383515, 2017). "Increased catabolism of ApoA1 is a hallmark of the functional impairment of ABCA1 in Tangier’s disease and in liver Abca1 deficient mice." (PMID 29144234, 2017). "So far, about twenty different mutations in the ABCA1 gene have been described, which are all associated with a Tangier’s disease-like phenotype." (PMID 28383515, 2017). "The importance of ABCA1 for the metabolic maturation of HDL was identified by the elucidation of the genetic cause of Tangier’s disease." (PMID 28342064, 2017). "The critical role of ABCA1 in HDL formation is evidenced by low HDL-C levels in heterozygous and homozygous patients of Tangier disease with loss-of-function mutations in the ABCA1 gene." (PMID 26522778, 2016). "In humans, a homozygous variant of ABCA1 present in Tangier disease is associated with a very low level of HDL cholesterol, a high concentration of triglycerides, and six times higher risk of cardiovascular disease." (PMID 25145866, 2014).
Tangier disease (continued). "Tangier disease (TD) is a rare autosomal recessive disorder, resulting from mutations in the ATP binding cassette transporter (ABCA1) gene." (PMID 25227739, 2014). "In this study using PolyPhen2 and MutPred in silico algorithms, we analyzed the genetic variations that can alter the expression and function of the ABCA1 gene that causes the allelic disorders familial hypoalphalipoproteinemia and Tangier disease." (PMID 25215231, 2014). "Genetic defects in ABCA1 causes Tangier disease, which exhibits a cholesterol accumulating phenotype similar to that found in NP-C and is characterized by HDL-deficiency." (PMID 23720634, 2013). "Functional mutations in ABCA1 cause Tangier disease, which is characterized by very low levels of plasma HDL apoA1." (PMID 23656756, 2013). "Patients with Tangier disease and ABCA1 mutation or mice with functional ablation of ABCA1 show an irregular inflammatory response." (PMID 23878415, 2013). "The importance of ABCA1 in cellular cholesterol transport became clear when mutations in the ABCA1 gene were discovered to cause Tangier disease, an HDL deficiency disorder." (PMID 23133551, 2012). "Mutations in ABCA1 have been associated with Tangier's disease and familial HDL deficiency, and individuals with high HDL-cholesterol levels have homozygous deficiencies of LIPC." (PMID 21858147, 2011). "Plasma apoD levels are significantly reduced in patientswith Tangier disease, a rare autosomal recessive disorder that is caused bymutations in the ATP-binding cassette A1 (ABCA1) gene." (PMID 19946382, 2009). "Following the discovery that mutations in ABCA1 cause Tangier Disease or familial hypoalphalipoproteinemia, more than 90 functional variants have now been reported to cause the low HDL-C phenotype." (PMID 19133158, 2009). "It is noteworthy that corneal lipid deposition is observed in three other human genetic disorders of cholesterol, specifically high density lipoprotein (HDL), metabolism: Niemann-Pick type C, LCAT deficiency (fish-eye disease) and ABCA1/Tangier Disease (TD)." (PMID 17668063, 2007). "Tangier disease is an extremely rare genetic disorder caused by mutations in the ABCA1 gene." (PMID 40476138, 2025). "At this time, the function of ABCA1 was not well understood, and it was unknown that a mutation in ABCA1 is what causes Tangier disease, which is a condition that causes cholesterol to become engorged in peripheral cells, accompanied by HDL deficiency." (PMID 40906448, 2025). "Notably, the variant p.L1097P (33 ± 14% of WT ABCA1 cholesterol efflux) was in 2015 reported homozygous in a 17-year-old male patient diagnosed with Tangier disease." (PMID 40617357, 2025). "However, the chromosomal defect of Tangier disease was later identified, followed by studies that confirmed that mutations in the ABCA1 gene are what causes Tangier disease." (PMID 40906448, 2025). "In addition, ABCA1 was identified to be the causative gene for Tangier disease (TD), a rare genetic disorder that exhibits severe HDL reduction and a high incidence of premature cardiovascular disease." (PMID 35669754, 2022). "In vitro experiments with skin fibroblasts derived from two Tangier disease patients carrying homozygous ABCA1 premature termination codon (PTC) or missense mutations leading to a loss of functional protein show an increased production of Aβ compared to control cells." (PMID 35477481, 2022). "Given the very low incidence of Tangier disease, it is impossible to asses whether TD patients are at increased risk factor for staphylococcal disease compared to non ABCA1 variant carriers/controls." (PMID 34321507, 2021). "Genetic mutations in ABCA1 (Tangier disease), LCAT (familial lecithin:cholesterol acyltransferase deficiency), ApoA1 (familial apolipoprotein (Apo) A1 deficiency), and UBIAD1 (Schnyder corneal dystrophy, SCD) all result in corneal accumulation of lipids including cholesterol." (PMID 34547023, 2021).
Tangier disease (continued). "However, patients with Tangier disease who express defective or deficient quantities of ABCA1 have reduced HDL biosynthesis and a dramatic reduction in the plasma residence time of HDL (0.22 days in patients with Tangier disease vs. 6 days in normal subjects)." (PMID 34360965, 2021). "Since ABCA1 is expressed in pancreatic β cells, glucose-stimulated insulin secretion might be impaired in Tangier disease patients with ABCA1 mutations." (PMID 31974794, 2020). "Until the present, about 97 mutations have been found in the ABCA1 gene, and a large number of them are linked with Tangier disease (TD), which is described as the accretion of cholesterol in reticuloendothelial cells that increases the risk of coronary heart disease." (PMID 33066695, 2020). "Thus, mutations in ABCA1 results in Tangier disease (TD), which presents with extremely low circulating HDL-C levels." (PMID 31487778, 2019). "Moreover, ABCA1–/– hamsters showed phenotypes resembling those with Tangier’s disease (TD) and familial high-density lipoprotein deficiency (FHD) in humans." (PMID 31487778, 2019). "With ABCA1 deficiency (i.e., Tangier disease), there is very mild corneal clouding (usually requiring a slit-lamp examination for its detection) and less abundant extracellular corneal stromal deposits, cholesterol, and phospholipid accumulation compared with genetic deficiency of LCAT." (PMID 31779197, 2019). "Mutations in ABCA1 have been associated with low levels of HDL as observed in Tangier Disease." (PMID 31846498, 2019). "Tangier disease and ABCA1-deficient patients also have an increased risk of vascular disease." (PMID 30373276, 2018). "Defective ABCA1-mediated transport in Tangier’s disease and ApoA-I deficiency are likewise associated with retinal pathologies that could result from impaired Ch transport within or out of the outer retina as represented in modules 2 and 3 of the RCD model." (PMID 28442497, 2017). "Homozygosity for mutations in the ABCA1 gene leads to Tangier disease." (PMID 28342064, 2017). "Mutations in ABCA1 cause Tangier disease, a rare genetic disorder that is characterized by plasma HDL cholesterol concentrations <5% of normal, ~50% reduction in plasma LDL cholesterol concentrations, cholesterol accumulation in macrophages, peripheral neuropathy, and hepatosplenomegaly." (PMID 29221444, 2017). "Homozygous mutations in ABCA1 cause Tangier disease, a rare HDL-deficiency syndrome." (PMID 26252223, 2015). "Tangier disease is a severe HDL deficiency syndrome that is caused by mutations in the ABCA1 gene." (PMID 26173179, 2015). "There are limited reports on the effects of ABCA1 mutations in the central nervous system, with premature atherosclerosis and neuropathy being the best documented symptoms of Tangier disease." (PMID 23720634, 2013). "Moreover, apoA‐I‐ and FAMP5‐mediated cholesterol effluxes were suppressed in circulating blood monocyte‐derived macrophages from an ABCA1‐deficient Tangier disease patient." (PMID 23709562, 2013). "Mutations in the cholesterol efflux pump ABCA1 have been associated with Tangier's disease." (PMID 22369239, 2012). "Moreover its activity is essential for formation of high-density lipoprotein (HDL) particles in vivo and mutations of ABCA1 lead to Tangier disease, an autosomal recessive trait characterized by HDL deficiency." (PMID 20030852, 2009). "Mutations in the ABCA1 gene are the cause of Tangier disease, a rare disorder that is characterized by the virtual absence of HDL in plasma of afflicted patients, the accumulation of cholesterol in tissue macrophages, and an increased incidence of cardiovascular disease." (PMID 20046702, 2008). "The loss of Abca1/g1 markedly increased neutrophil recruitment and extracellular trap (NETosis) formation in lesions, and patients with a loss of function mutations in ABCA1 (Tangier disease) exhibit increased myeloid cholesterol content and inflammasome activation." (PMID 37759631, 2023).
Tangier disease (continued). "As ABCA1 plays a key role in effluxing cholesterol from cells, ABCA1loss-of-function results in diminished cholesterol removal from peripheraltissues, contributing to excessive accumulation of cholesterol in the body andincreased risk of developing atherosclerosis in patients with Tangier disease." (PMID 19946382, 2009). "ATP-binding cassette transporter A1 (ABCA1) has been identified as the molecular defect in Tangier disease." (PMID 36831097, 2023). "Classic ABCA1 pathogenic variants are associated with most severe phenotypic presentations while heterozygous carriers may result in mitigated phenotypes with reduced HDL-C levels that are intermediate between Tangier disease and normal, so it is believed that it may be underdiagnosed." (PMID 37048678, 2023). "The dysfunction of ABCA1 in Tangier disease results in cholesterol accumulation in the peripheral tissue and causes severe HDL deficiency." (PMID 35057469, 2022). "Compound homozygous or heterozygous mutations in the ABCA1 gene cause Tangier disease (TGD) (OMIM, 205,400), a rare autosomal recessive disorder characterized by extremely low plasma HDL-C levels (HDL-C < 5 mg/dL) and ApoA- I ≤ 10 mg/dL and, increased risk of early-onset CAD." (PMID 35743896, 2022). "The identification of ABCA1 loss of function mutations in patients with HDL-deficiency syndromes, including Tangier disease, confirmed the role of ABCA1 in cellular cholesterol homeostasis." (PMID 35477481, 2022). "The key role of ABCA1 in RCT and HDL metabolism is evident as ABCA1 gene mutations causing Tangier disease are associated with extremely low plasma HDL-C levels, a characteristic feature of the disease." (PMID 33562440, 2021). "ABCA1 is involved in efflux of cholesterol and phospholipids from cells to HDL and its deficiency causes Tangier disease characterized by orange tonsils, hepatosplenomegaly, and enhanced atherosclerosis." (PMID 31974794, 2020). "In this study, we found that when ABCA1 is defective (Tangier disease) there is secondary inhibition of the NPC disease pathway, linking these two diseases at the level of cellular pathophysiology." (PMID 31707734, 2020). "Mutations in these genes are associated with diseases, including cystic fibrosis (ABCC7/CFTR), Tangier disease (ABCA1/CERP), Dubin–Johnson syndrome [ABCC2/multidrug resistance‐associated protein (MRP2)] and gout [ABCG2/breast cancer resistance protein (BCRP)]." (PMID 33128234, 2020). "Screens for small molecule treatments have been instigated, including for Tangier disease (ABCA1), gout (ABCG2), Stargardt eye disease (ABCA4), progressive familial intrahepatic cholestasis type 2 (ABCB11), and congenital hyperinsulinemia." (PMID 30659068, 2019). "Using the example of the ATP-binding cassette transporter A1 (ABCA1) gene (Tangier disease), we describe our algorithm for functionally significant sequence finding." (PMID 31234415, 2019). "More importantly, results from Tangier disease patients and liver-specific ABCA1-knockout mice suggest that hepatic ABCA1 is the most important source of nascent ApoA1 and is absolutely required for the maintenance of the majority of the plasma HDL pool." (PMID 27136542, 2016). "We also tested the ability of LXR agonist to inhibit inflammatory gene expression in skin fibroblasts from a patient with Tangier disease that lack functional ABCA1 protein." (PMID 26173179, 2015). "First, recessive mutations in ABCA1 cause extreme reduction in HDL-C, termed Tangier Disease or hypoalphalipoproteinemia; several of these variants were discovered in Finnish families." (PMID 24497850, 2014). "Tangier disease (TD) (OMIM #205400) is a rare autosomal recessive disorder, resulting from mutations in the ATP binding cassette transporter (ABCA1) gene, mapped to chromosome 9q22-q31." (PMID 25227739, 2014).